IMPDH2 (inosine monophosphate dehydrogenase 2)
Diseases named in the same sentence as IMPDH2 in open-access papers (continued):
Sharing a sentence is not in itself a finding about the gene and the disease.
cancer (continued). "We propose that B7-H3 depletion in these types of tumours might drive pro-tumorigenic activity through downstream IMPDH2 activation and the destabilisation of ZO-1 at cell–cell adhesions to promote growth and invasion, as has been suggested in other cancer types." (PMID 37444640, 2023). "Interestingly, MPA treatment also resulted in a significant reduction in plasma-membrane-associated IMPDH2 in A549 and H358 cells, suggesting that this may represent the key active pool of IMPDH2 in cancer cells." (PMID 37444640, 2023). "However, the role and regulation of IMPDH2 in RRs remains unclear, in both normal epithelial and cancer cells." (PMID 37444640, 2023). "The immunosuppressive potential of IMPDH2 inhibitors, such as MPA and MMF, is well documented and an important consideration in cancer therapy." (PMID 41154443, 2025). "We discovered that two cancer-driving proteins, ALK and SRC, directly modify and activate a key metabolic enzyme called IMPDH2." (PMID 41154443, 2025). "IMPDH2 activates PI3K/Akt and Wnt/β-catenin pathways to promote progression or drive EMT processes in diverse cancers." (PMID 35964092, 2022). "Inosine monophosphate dehydrogenase type II (IMPDH2) has been shown to play critical roles in the development and progression of several human cancers." (PMID 28389646, 2017). "Unlike existing drugs, Comp-10 reduces IMPDH2 protein levels, blocks its activity, and prevents the formation of harmful enzyme structures in cancer cells." (PMID 41154443, 2025). "We observed that IMPDH1, but not the related gene IMPDH2, was significantly overexpressed in all 15 cancers, implying the key role of IMPDH1 in tumourigenesis." (PMID 36629054, 2023). "Surprisingly, B7-H3 depletion from cancer cells does not affect growth or migration in 2D but promotes invasion in 3D models in an IMPDH2-dependent manner." (PMID 37444640, 2023). "Given the observed B7-H3/IMPDH2-dependent effects on glutathione-dependent metabolism and GTP, we sought to determine whether these molecules may co-operate to enable cancer cell chemoresistance." (PMID 37444640, 2023). "Conversely, RRs were not seen under basal conditions in either cancer cell line, and IMPDH2 was instead cytoplasmic or localised in the plasma membrane." (PMID 37444640, 2023). "Future studies to determine whether a direct relationship exists between IMPDH2, GTP, and oxidative stress will be required to understand how these pathways might converge in cancer cell stress responses." (PMID 37444640, 2023). "Here, we found that IMPDH1, but not the related gene IMPDH2, was significantly overexpressed in 15 cancer types." (PMID 36629054, 2023). "However, the role of IMPDH1 in cancer, especially in CRC, has been largely ignored because IMPDH1 is less expressed than IMPDH2 in most tissues." (PMID 36629054, 2023). "Among these anti-cancer targets, 3-phosphoinositide-dependent protein kinase-1(PDPK1), MMP1, MMP2, MMP3, nitric oxide synthase (NOS2), and inosine-5′-monophosphate dehydrogenase 2 (IMPDH2) showed similar binding affinity with bruceantin as that of some marketing drugs." (PMID 24429698, 2014). "The data presented here suggest that in the absence of immune cells, B7-H3 could maintain cancer cell growth by regulating IMPDH2 localisation and potential activity, and subsequently the de novo purine biosynthetic pathway, resulting in increased GTP levels." (PMID 37444640, 2023). "Given that all 16 enzymes analyzed localized to the leading edge and colocalized with IMPDH1 and/or IMPDH2, our data suggests the formation of a GTP- and possibly also an ATP-specific metabolic compartment—GTP and ATP metabolons, respectively—at the leading edge of the motile cancer cells." (PMID 33224873, 2020).
cancer (continued). "A few IMPDH2 inhibitors are currently FDA-approved, although not for the treatment of cancer; for example, ribavirin is used for the treatment of viral infections while mycophenolate mofetil is used as an immunosuppressant post organ transplant." (PMID 39774345, 2025). "Unlike IMPDH1, IMPDH2 expression is increased in neoplastic cells, and modulation of IMPDH2 levels alters intracellular GTP pools and affects cancer cell proliferation and/or invasion." (PMID 34667203, 2021).
tumor (39 papers, 2008 to 2026). "When PSMD14 is inhibited genetically or pharmacologically, IMPDH2 stability diminishes, causing impaired nucleotide metabolism, mitochondrial dysfunction, increased DNA damage signaling, and reduced tumor malignancy." (PMID 41608571, 2026). "We proposed that the potential function of RPTOR and IMPDH2 in regulation of tumor immune cell infiltration, and their association with the cetuximab sensitivity is deserved to be further explored in the future." (PMID 38302471, 2024). "Changes in IMPDH1 and IMPDH2 expression cause abnormal guanine biosynthesis, affecting tumor cells physiologically." (PMID 37215997, 2023). "We propose that B7-H3, through association with IMPDH2, can protect cells against oxidative stress and influence purine metabolism, leading to the modulation of tumour growth and invasion." (PMID 37444640, 2023). "Increased serum levels of IMPDH2 were significantly associated with Gleason ≥8 PCa, suggesting its potential as a serological tumor marker." (PMID 36765747, 2023). "Functionally, IMPDH2 is the rate-limiting enzyme in guanine nucleotide synthesis and has been associated with tumor progression, as well as cellular proliferation and tumorigenesis." (PMID 34791326, 2022). "In addition, disruption of IMPDH polymers by a single point mutation Y12C in IMPDH2 is sufficient to alter the metabolic status of tumours and reduce tumour growth." (PMID 40186514, 2025). "AVN944 (VX-944, Vertex Pharmaceuticals, Cambridge, MA, USA) is an IMPDH2 inhibitor designed to disrupt the metabolic pathways crucial for tumor cell proliferation and survival." (PMID 41522344, 2026). "To confirm that the anti-tumor activity of AVN944 is attributable directly to inhibition of IMPDH2, we treated TC71 and SK-ES-1 cells with 1 μM MPA and analyzed the effects on the cell cycle and apoptosis over 96 h." (PMID 41522344, 2026). "Combining an IMPDH2 inhibitor with an ATR kinase inhibitor caused synergistic replication stress in vitro and suppressed MCC tumor growth in vivo, suggesting a therapeutic strategy to exploit replication stress in MCC." (PMID 40723224, 2025). "While Comp-10 inhibits IMPDH2 activity, disrupts R/R formation, and prevents tumor cell proliferation, its effects on the immune system, particularly on anti-tumor immune responses, are not yet fully understood." (PMID 41154443, 2025). "In CRC, pharmacological inhibition of IMPDH2 suppresses tumor growth and reverses oxaliplatin resistance, underscoring its therapeutic potential." (PMID 40626716, 2025). "Once the tumours were palpable, the mice were treated with control, oxaliplatin monotherapy, the IMPDH2 inhibitor MMF monotherapy, or a combination of oxaliplatin (10 mg/kg every 3 days) and MMF (120 mg/kg twice a day) for 3 weeks." (PMID 38310229, 2024). "To explore the possible roles of IMPDH2, we first examined the expression of IMPDH2 in 29 types of human tumour tissues and corresponding normal tissues using the TCGA and TIMER databases." (PMID 38310229, 2024). "We next explored the lung tissue expression of IMPDH1 and IMPDH2 among normal (n = 391), tumor (n = 1,865), and metastatic (n = 8) tissue samples from data available within TNMplot." (PMID 39366383, 2024). "We report that histone H4, HBA1, IMPDH2, and two unidentified m/z values (m/z 1305.840 and 1661.060) are more abundant in tumour tissues of CRLM patients with poor survival." (PMID 38492056, 2024). "Accumulating evidence from previous investigations has underscored the substantial elevation of IMPDH2 expression, which correlates closely with tumor progression and a poor prognosis in a diverse array of malignancies." (PMID 39085725, 2024). "In particular, we observed that the fold change in IMPDH1 expression in tumours compared to normal tissues was significantly higher than the fold change in IMPDH2 expression in CRC, implying a pivotal role for IMPDH1 in tumourigenesis." (PMID 36629054, 2023).
tumor (continued). "Nude mice were injected subcutaneously with 5637 cells knocked down IMPDH1 and IMPDH2 to construct the subcutaneous tumor model." (PMID 37215997, 2023). "GTP is particular important for protein synthesis and required in rapidly dividing tumor cells, and its biosynthesis is manipulated by IMPDH2." (PMID 37752569, 2023). "IMPDH2 is an important enzyme in guanine nucleotide biosynthesis and up-regulated in a variety of tumor cells." (PMID 38072991, 2023). "The molecular mechanisms suggested that TMTC3 facilitated tumor angiogenesis by regulating Rho GTPase/STAT3/VEGFA pathway mediated by interacting with IMPDH2 Bateman domain." (PMID 37752569, 2023). "It has been suggested that IMPDH2 can be used not only as a biomarker for tumor diagnosis, but also as a potential therapeutic target for the treatment of malignant tumors." (PMID 35416106, 2022). "Consistently, in tumor cells used in our study, IMPDH2 mRNA levels were significantly higher than IMPDH1 mRNA levels although in non-transformed counterparts of these cells the IMPDH2/IMPDH1 level ratio was not as high." (PMID 34667203, 2021). "IMPDH1 is generally expressed in normal human leukocytes and lymphocytes, whereas IMPDH2 is generally upregulated in tumor tissues and proliferating cells." (PMID 30518405, 2018). "While the IMPDH2 mutation generally leads to downregulation of glycolytic pathway and PPP enzyme mRNA levels in most mutant HEC‐1‐A, CE81T, and HeLa cell‐derived tumours, this trend is less apparent in mutant HCT116 cell‐derived tumours." (PMID 40186514, 2025). "IMPDH2 upregulation was also found to be associated with key clinical-pathological features, including pre-chemotherapy alpha-fetoprotein (AFP) levels, presence of preoperative metastasis, and the pre-treatment extent of tumor (PRETEXT) staging system." (PMID 39085725, 2024). "To further investigate whether pharmacological inhibition of IMPDH2 could reverse oxaliplatin resistance in vivo, we established subcutaneous xenograft tumour models by inoculating HCT8/L-OHP cells into the right flank of nude mice." (PMID 38310229, 2024). "In addition, protein levels of IMPDH1 and IMPDH2 in mouse tumor tissues were markedly down-regulated by MMF (p < 0.001), but were only fine-tuned by GDNT." (PMID 38419324, 2024). "It would be interesting to determine in future studies whether B7-H3 forms a direct complex with IMPDH2 and to manipulate this complex directly to explore tumour cell behaviour in a 3D context." (PMID 37444640, 2023). "Additionally, to elucidate the effect of IMPDH2 on tumor growth in vivo, xenograft growth assays were performed in nude mice by subcutaneous injection of LoVo/IMPDH2 cells and control cells." (PMID 30518405, 2018). "Furthermore, IMPDH2 contributes to cell proliferation in a variety of cell lines and tissues such as activated lymphocytes and tumor cells." (PMID 25714999, 2015). "It was found that the organoid cultured in vitro could largely maintain the DNA methylation patterns of gene promoter regions as those of in vivo tumor tissues, including the genes BCL2L1, IMPDH2, and TGFBI, which have been reported to be associated with CRC progression." (PMID 37345888, 2024). "Thus, IMPDH2 overexpression is closely related to tumor progression." (PMID 35416106, 2022). "Moreover, IMPDH2, which is synthesized by guanine nucleotide rate-limiting enzymes, provides guanine nucleotides for T cell proliferation and is highly expressed in proliferating tumor tissues." (PMID 32817748, 2020). "In addition to these changes, in the serum-depleted proteome we observed downregulation of keratin 8, and upregulation of vimentin, the glycolytic enzymes enolase and pyruvate kinase (PKM2) and tumor progression-related inosine-5’-monophosphate dehydrogenase 2 (IMPDH2) enzyme." (PMID 28536624, 2016). "While specific NPC IMPDH roles remain unstudied, it is notable that IMPDH2 is expressed in NPC cell lines and in tumor tissues." (PMID 40367275, 2025).
tumor (continued). "Xenograft experiment was performed on mice, followed by drug administration, measurement of tumor growth and determination of CES2, IMPDH1 and IMPDH2 expressions." (PMID 38419324, 2024). "Targeted inhibition of IMPDH2 by mycophenolic acid (MPA) or mycophenolate mofetil (MMF) enhanced cell apoptosis in vitro and decreased in vivo tumour burden when combined with oxaliplatin treatment." (PMID 38310229, 2024). "Guanosine accelerated the malignant progression of ICC inhibition of purine metabolism-related genes, PPAT and IMPDH2, suppressed the malignant phenotype in HCCC-9810 cells, and inhibited tumor growth." (PMID 36711025, 2023). "AFF4 depletion impaired tumor formation, and rescued simultaneous expression of HPRT1 and IMPDH2 recovered tumor formation and tumor growth." (PMID 37063434, 2023). "The tumor from this SCLC subtype expressed an increased guanosine biosynthetic enzyme known as inosine monophosphate dehydrogenase 1 and 2 (IMPDH1 and IMPDH2)." (PMID 33854965, 2021). "Thus, we performed an additional LC–MS/MS analysis to measure nucleotide levels in three other tumour pairs (Ms 3, Ms 13 and Ms 15) and cultured HeLa cells to see if GTP levels are attenuated in IMPDH2 mutant tissues and cells." (PMID 40186514, 2025). "We observed that the expression of IMPDH1 and IMPDH2 did not correlate within patient samples and between tumor site." (PMID 39366383, 2024). "We propose that B7-H3 plays important non-immunogenic roles in tumour cells to regulate the balance of active and inactive IMPDH2, which is critical to cell survival in response to extracellular stress." (PMID 37444640, 2023). "Further study revealed that overexpression of IMPDH2 significantly promoted the proliferation, invasion, migration and epithelial-mesenchymal transition (EMT) of CRC cells in vitro and accelerated xenograft tumour growth in nude mice." (PMID 30518405, 2018). "While this study did not specifically examine LMP1 expression in NPC tumor tissues, it would be of interest to know whether cases with elevated IMPDH2 levels also exhibited abundant LMP1 expression." (PMID 40367275, 2025). "Interestingly, IMPDH1 has been shown to be ubiquitously expressed in many different tissues, while IMPDH2 is upregulated in proliferating tissues, which could include DMG tumor tissue." (PMID 38594734, 2024). "One recent study observed a large increase in IMPDH2 but not IMPDH1 in GBM compared to control brains and proposed IMPDH2 as the molecular link between GTP biosynthesis, the increased anabolic process of rRNA and tRNA, and tumor malignancy in GBM." (PMID 38892179, 2024). "Note that in the absence of tumor formation at day 3, the expression of PPAT, IMPDH1, IMPDH2, DHODH but not PAICS are all statistically significantly elevated with MYC induction." (PMID 18628958, 2008). "Furthermore, IHC was performed using an antibody against Ki67 and we observed that simultaneous expression of HPRT1 and IMPDH2 promoted tumor growth from cells lacking AFF4, proving a genetic axis of AFF4/HPRT1& IMPDH2 is existed in PDAC cells." (PMID 37063434, 2023).
neurodevelopmental disorder (5 papers, 2021 to 2025). A behavioral and cognitive disorder with onset during the developmental period that involves impaired or aberrant development of intellectual, motor, or social functions. "Indeed, recent studies implicate de novo IMPDH2 mutations in the etiology of neurodevelopmental disorders." (PMID 39075237, 2024). "Furthermore, heterozygous mutations in IMPDH2 have recently been associated with neurodevelopmental disorders and mutations in IMPDH1 lead to common retinal degenerative disorders (i.e., retinitis pigmentosa and leber congenital amaurosis)." (PMID 39075237, 2024). "In the case of IMPDH2, the defect results in neurodevelopmental disorders." (PMID 37414152, 2023).
infection (2 papers, 2019 to 2021). The state of being infected such as from the introduction of a foreign agent such as serum, vaccine, antigenic substance or organism. "However, IMPDH2 that interacts with and supplies PARP1 and PARP2 with NAD+ substrates for enzymatic reactions significantly enhances polymerase activity during infection." (PMID 31015836, 2019).
endocrine system disorder (1 paper, 2010). A disease involving the endocrine system. "IPA data base showed RETNLB and FDPs were associated with endocrine system disorders; CAPG, ACOT9, FDPS, and IMPDH2 were associated with genetics disorder." (PMID 21172007, 2010).
IMPDH2 also shares sentences with these, for which no sentence is quoted: hematologic malignancies (2 papers); non-small cell lung carcinoma (2); ovarian carcinoma (2); Tremor (2); acute myelogenous leukemia (1); anaplastic large cell lymphoma (1); atherosclerosis (1); brain diseases (1); breast adenocarcinoma (1); Breast Invasive Carcinoma (1); chronic lymphocytic leukemia (1); diffuse midline glioma (1); gastric cancer (1); hematological cancers (1); heroin addicts (1); kidney cancer (1); kidney failure (1); liver cancer (1); mantle cell lymphoma (1); metastatic prostate carcinoma (1); musculoskeletal system diseases (1); nephritis (1); nephrosis (1); neurological disease (1); Onset (1); osteoarthritis (1); primary effusion lymphoma (1); protein (1); rectal tumor (1); rectum adenocarcinoma (1).
A further 3 diseases each share a sentence with IMPDH2 in 1 paper.